Y_RNA (Y RNA )
Gene: Miscellaneous RNA gene on chromosome 7 (103,434,994 to 103,435,092, reverse strand). Ensembl gene ENSG00000252047.
Homologues: Orthologues: guinea pig Y_RNA (94% identical). Paralogues in human: Y_RNA (94% identical), Y_RNA (91% identical), RNY3 (90% identical), Y_RNA (90% identical), Y_RNA (89% identical), RNY3P1 (88% identical), Y_RNA (88% identical), Y_RNA (87% identical), RNY3P16 (86% identical), RNY3P2 (86% identical), Y_RNA (86% identical), Y_RNA (85% identical), and 97 more.